LTV1 (LTV1 ribosome biogenesis factor)
Description:
Essential for ribosome biogenesis.
Synonyms: C6orf93; FLJ14909; dJ468K18.4; IPHAK
Tractability: Small molecule: a structure with a bound ligand is known. PROTAC: ubiquitination databases record sites on it; its protein half-life has been measured.
Gene: Protein-coding gene on chromosome 6 (143,843,326 to 143,863,812, forward strand). Ensembl gene ENSG00000135521.
Subcellular location: Cytoplasm
Subcellular location (Human Protein Atlas): Cytosol; Nucleoplasm
Pathways (Reactome):
Metabolism of RNA: Major pathway of rRNA processing in the nucleolus and cytosol
Gene Ontology:
Molecular function: protein binding
Biological process: ribosomal small subunit biogenesis; ribosomal small subunit export from nucleus; ribosome biogenesis
Cellular component: cytoplasm; cytosol; nucleoplasm; nucleus; preribosome, small subunit precursor
Genetic constraint (gnomAD): Loss-of-function variants: 28 observed, 51.47 expected, observed/expected ratio (o/e) 0.54, 90% interval 0.4 to 0.75. The upper end of that interval is the gene's LOEUF score, 0.75, which puts it in group 3 of 6, group 1 being the genes least tolerant of losing a copy. Missense variants: 451 observed, 529.79 expected, observed/expected ratio (o/e) 0.85, 90% interval 0.79 to 0.92. Synonymous variants: 158 observed, 185.6 expected, observed/expected ratio (o/e) 0.85, 90% interval 0.75 to 0.97.
Homologues: Orthologues: chimpanzee LTV1 (99% identical), macaque LTV1 (97% identical), dog LTV1 (89% identical), pig LTV1 (86% identical), mouse Ltv1 (85% identical), rat Ltv1 (84% identical), rabbit LTV1 (83% identical), tropical clawed frog ltv1 (66% identical), zebrafish ltv1 (61% identical), Drosophila melanogaster LTV1 (43% identical), Caenorhabditis elegans T23D8.3 (31% identical).
Diseases named in the same sentence as LTV1 in open-access papers:
LTV1 is named in the same sentence as 8 diseases in open-access papers, as found by Europe PMC text mining. Sharing a sentence is not in itself a finding about the gene and the disease. The quoted sentences say what the papers report.
leukemia (2 papers, 2022 to 2025). A malignant (clonal) hematologic disorder, involving hematopoietic stem cells and characterized by the presence of primitive or atypical myeloid or lymphoid cells in the bone marrow and the blood. "These involve genes which are known to be leukemia drivers (such as FAT1, NOTCH1, PHF6, FLT3), and can activate signaling pathways that push the cells to multiply faster, as well as genes involved in ribosome biogenesis or translational control (such as WDR36 and LTV1)." (PMID 36482893, 2022).
breast carcinoma (1 paper, 2021). "In one study, it was shown that LTV1 was substoichiometric in breast cancer cells, producing reduced RPS10 and RACK1 ribosomes." (PMID 34923969, 2021). "Furthermore, knockdown of LTV1 attenuated SR-3029-induced apoptosis in MDA-MB-231 breast cancer cells and restored drug sensitivity." (PMID 34923969, 2021).
clear cell renal cell carcinoma (1 paper, 2021). "We hypothesized that LTV1 and EIF3A could jointly promote the tumorigenesis of clear cell renal cell carcinoma and significantly affect the prognosis." (PMID 34923969, 2021).
glioma (1 paper, 2020). A benign or malignant brain and spinal cord tumor that arises from glial cells (astrocytes, oligodendrocytes, ependymal cells). "Interestingly, glioma cancer cells have reduced levels of LTV1 and produce ribosomes lacking RPS3, RPS10, and RACK1." (PMID 33334055, 2020).
cancer (4 papers, 2020 to 2023). A tumor composed of atypical neoplastic, often pleomorphic cells that invade other tissues. "This Achilles heel is exploited by cancer cells that downregulate Ltv1." (PMID 36790396, 2023). "Thus, the cancer-associated Rps15_S136F mutation, which leads to increased misinitiation at non-AUG codons, may perturb Rps15 directly, or affect how Ltv1 (or other, yet undescribed factors) regulates the interaction between Rps15 and the loop in Tsr1." (PMID 37503067, 2023).
respiratory diseases (1 paper, 2019). "Although studies in yeast describe LTV1 as a conserved 40S-associated biogenesis factor that functions in small subunit nuclear export, a specific role for LTV1 in respiratory diseases is not known." (PMID 31791327, 2019).
tumour (1 paper, 2021). "The expression and prognostic value of LTV1 was verified in ccRCC, and the results confirmed that LTV1 had higher expression in tumour tissue." (PMID 34923969, 2021).
LTV1 also shares sentences with these, for which no sentence is quoted: asthma (1 paper).